MIR570 (microRNA 570)
Synonyms: hsa-mir-570; MIRN570
Gene: MicroRNA gene on chromosome 3 (195,699,401 to 195,699,497, forward strand). Ensembl gene ENSG00000207650.
Diseases named in the same sentence as MIR570 in open-access papers:
MIR570 is named in the same sentence as 1 disease in open-access papers, as found by Europe PMC text mining. Sharing a sentence is not in itself a finding about the gene and the disease. The quoted sentences say what the papers report.
Right ventricular hypertrophy (1 paper, 2022). In this case the right ventricle is more muscular than normal, causing a characteristic boot-shaped (coeur-en-sabot) appearance as seen on anterior- posterior chest x-rays. "CircRNA-0068481 can promote the pathological progression of right ventricular hypertrophy (VH) by regulating the expression of MIR570." (PMID 36299595, 2022).